MASP1 (MBL associated serine protease 1)
Description:
Precursor of a serum protease that activates the complement pathway of the complement system, a cascade of proteins that leads to phagocytosis and breakdown of pathogens and signaling that strengthens the adaptive immune system. [Isoform MASP-1]: Serine protease that activates the lectin pathway of the complement system, a cascade of proteins that leads to phagocytosis and breakdown of pathogens and signaling that strengthens the adaptive immune system. The lectin complement system is activated following association of lectins, such as MBL2, FCN1, FCN2 or FCN3, to carbohydrates on the pathogen surface. Following autoproteolytic processing in response to lectin-binding to pathogen carbohydrates, catalyzes cleavage and activation of MASP2, the next component of the lectin complement pathway. [Isoform MASP-3]: Serine protease that activates the alternative pathway of the complement system, a cascade of proteins that leads to phagocytosis and breakdown of pathogens and signaling that strengthens the adaptive immune system. The alternative complement pathway acts as an amplification loop that enhances other complement pathways. Isoform MASP-3 specifically catalyzes cleavage and activation of factor D (CFD), the protease that initiates the alternative complement pathway.
Synonyms: RaRF; CRARF; CRARF1; PRSS5; MASP; Map44; MASP-3; MAP-1; 3MC1; MAP1; MASP3
Tractability: Small molecule: a structure with a bound ligand is known. Antibody: UniProt places it where antibodies can reach, with high confidence; its Gene Ontology location is reachable by antibodies, with high confidence; UniProt predicts a signal peptide or a membrane-spanning region. PROTAC: a small molecule that binds it is known.
Target class: Enzyme; Hydrolase
Gene: Protein-coding gene on chromosome 3 (187,217,282 to 187,291,980, reverse strand). Ensembl gene ENSG00000127241.
Subcellular location: Secreted; Secreted (Isoform MASP-1); Cell surface; Secreted (Isoform MASP-3)
Subcellular location (Human Protein Atlas): Cytosol; Nucleoplasm; Predicted to be secreted
Pathways (Reactome):
Immune System: Ficolins bind to repetitive carbohydrate structures on the target cell surface; Initial triggering of complement; Lectin pathway of complement activation
Disease: SARS-CoV-2 activates/modulates innate and adaptive immune responses
Vesicle-mediated transport: Scavenging by Class A Receptors
Gene Ontology:
Molecular function: calcium ion binding; calcium-dependent protein binding; peptidase activity; protein binding; protein homodimerization activity; serine-type endopeptidase activity
Biological process: complement activation, lectin pathway; zymogen activation; complement activation; proteolysis
Cellular component: cell surface; cytosol; extracellular region; nucleoplasm; symbiont cell surface
Genetic constraint (gnomAD): Loss-of-function variants: 56 observed, 80.01 expected, observed/expected ratio (o/e) 0.7, 90% interval 0.56 to 0.87. The upper end of that interval is the gene's LOEUF score, 0.87, which puts it in group 3 of 6, group 1 being the genes least tolerant of losing a copy. Missense variants: 876 observed, 955.11 expected, observed/expected ratio (o/e) 0.92, 90% interval 0.87 to 0.97. Synonymous variants: 359 observed, 373.94 expected, observed/expected ratio (o/e) 0.96, 90% interval 0.88 to 1.05.
Gene-disease validity (ClinGen):
ClinGen rates the evidence that MASP1 causes each of these diseases.
3MC syndrome 1 (autosomal recessive): Definitive. Any 3MC syndrome in which the cause of the disease is a mutation in the MASP1 gene.
Homologues: Orthologues: macaque MASP1 (97% identical), pig MASP1 (92% identical), dog MASP1 (92% identical), rabbit MASP1 (92% identical), guinea pig MASP1 (90% identical), rat Masp1 (90% identical), chimpanzee MASP1 (73% identical), mouse Masp1 (66% identical), zebrafish masp1 (54% identical), tropical clawed frog masp1 (53% identical). Paralogues in human: MASP2 (41% identical), PRRG2 (7% identical).
Diseases named in the same sentence as MASP1 in open-access papers:
MASP1 is named in the same sentence as 147 diseases in open-access papers, as found by Europe PMC text mining. Sharing a sentence is not in itself a finding about the gene and the disease. The quoted sentences say what the papers report.
3MC syndrome (23 papers, 2012 to 2025). "Mutations in MASP1 are associated with 3MC syndrome, which causes various developmental defects, including CLP." (PMID 41378467, 2025). "To date, 30 patients from 22 families presenting with 3MC syndrome 1 caused by MASP1 mutations have been reported in the literature." (PMID 37892645, 2023). "On the other hand, lack of MASP-3 activity due to mutations in MASP-3-specific exon of the MASP1 gene results in 3MC syndrome." (PMID 36052069, 2022). "As mentioned, so far 11 mutations in the COLEC11 gene, three in the COLEC10 gene, and 16 in the MASP1/3 gene associated with 3MC syndrome have been described." (PMID 32751929, 2020). "Deficiency of MASP-1/3 or its complex partner CL-K1 leads to the development of 3MC syndrome, which is characterized by unusual facial features and problems affecting other tissues and organs of the body." (PMID 29892304, 2018). "We previously reported that lectin complement pathway genes COLEC11 and MASP1/3 are mutated in 3MC syndrome patients." (PMID 28301481, 2017). "We previously demonstrated that mutations in COLEC11 and MASP1/3 lectin complement pathway related genes are causative of 3MC syndrome in 11 families and 16 patients." (PMID 28301481, 2017). "We previously reported that lectin complement pathway genes COLEC11 and MASP1/3 were mutated in 3MC syndrome patients." (PMID 28301481, 2017). "We previously reported that mutations in COLEC11 and MASP1/3 genes were responsible for several cases of 3MC syndrome." (PMID 28301481, 2017). "Three missense variants found in this study affect only the SP domain of MASP-3 and support the earlier observation that the disruption of MASP-3 with normal MASP-1 and MAp44 is sufficient to cause 3MC syndrome." (PMID 26419238, 2015). "Loss-of-function of MASP-3 due to congenital mutations in MASP-3-specific exon of the MASP1 gene results in human 3MC syndrome characterized by a spectrum of developmental features, including developmental delay, growth retardation, intellectual disability, and characteristic facial atypia." (PMID 36052069, 2022). "Rare mutations in a highly conserved region of exon 12 of the MASP1 gene, which is exclusive of MASP-3 and encodes the serine protease domain of this protein, cause the 3MC1 (Malpuech-Michels-Mingarelli-Carnevale) syndrome, pointing to an important role in ectodermal development." (PMID 32240160, 2020). "Other MASP1/3 polymorphisms have been associated with the 3MC syndrome." (PMID 32635486, 2020). "Later, several other MASP1/3 gene mutations were found within families affected by 3MC syndrome." (PMID 32635486, 2020). "Rare mutations in the MASP-3 encoding part of the MASP1 gene have been directly linked to the 3MC syndrome, an autosomal recessive congenital syndrome, with features of facial dysmorphic traits, cleft lip and palate, post-natal growth deficiency, cognitive impairment, and hearing loss." (PMID 24023860, 2013). "Although the mechanism of postnatal growth failure in 3MC syndrome is unclear, MASP1 has been indicated to play a role in extracellular biological processes, and its molecular function is related to calcium ion binding and ECM components." (PMID 37892645, 2023). "To date, 16 mutations in MASP-1/3, 12 mutations in COLEC11 and three in COLEC10 associated with 3MC syndrome have been identified." (PMID 32751929, 2020). "Initially it was shown that in patients with 3MC syndrome, with combined MASP-1 and MASP-3 deficiency, the AP was functional while the LP was totally non-functional." (PMID 32153567, 2020). "Variants of the MASP1 gene, resulting in the loss of the activity of MASP-3, cause the 3MC syndrome, characterized by serious craniofacial, genital, and often mental defects." (PMID 30135690, 2018). "MASP1 on chromosome 3q24 encodes for three isoforms, mannan-binding lectin serine peptidase 1 (MASP1), MASP3, and MASP4, and is a disease-causing a gremlin mutation, resulting in 3MC syndrome (MIM#600521)." (PMID 37892645, 2023).
3MC syndrome (continued). "3MC syndrome is a rare genetic disorder inherited through an autosomal recessive inheritance pattern caused by mutations in one of three genes: COLEC11, COLEC10, and MASP1." (PMID 34589314, 2021). "This may be supported by the relationship between MASP1/3, COLEC10, and COLEC11 mutations and the incidence of 3MC syndrome, associated with craniofacial abnormalities." (PMID 32751929, 2020). "This is supported by relationships between MASP1/3, COLEC10, and COLEC11 gene mutations and the incidence of 3MC syndrome, associated with craniofacial abnormalities such as radioulnar synostosis high-arched eyebrows, cleft lip/palate, hearing loss, and ptosis." (PMID 32751929, 2020). "Recessive loss of function mutations in MASP1, resulting in impairment of MASP3, cause 3MC syndrome; a rare disorder characterized by facial dysmorphism, and commonly presenting cleft lip and palate, postnatal growth deficiency, hearing loss, and cognitive impairment." (PMID 31170158, 2019). "Mutations in two genes, MASP1 (MIM 600521) and COLEC11 (MIM 612502), which both encode proteins playing important roles in the lectin complement pathway, were found to be responsible for 3MC syndrome." (PMID 26419238, 2015). "An unexpected important role of the MASP-3 protease in early developmental processes has been recently suggested by the recent discovery of a link between mutations in the MASP1/3 gene and the 3MC syndrome, a rare autosomal recessive syndrome characterized by various developmental disorders." (PMID 23861840, 2013). "Several different potentially deleterious mutations in genes of the lectin arm of the complement system - such as MASP1, COLEC10, and COLEC11 genes – have been described in patients with 3MC syndrome." (PMID 32116493, 2020). "Further studies, however, are necessary to further understand the mechanisms by which dysfunctional MASP1, COLEC10, and COLEC11 genes may lead to 3MC syndrome." (PMID 32116493, 2020). "Further studies, however, are necessary to better understand the mechanisms by which dysfunction of MASP1/3, COLEC10, and COLEC11 genes may lead to the 3MC syndrome." (PMID 32751929, 2020). "Several neural crest regulatory molecules are known to cause ear/kidney syndromes with variable expression of both ear and kidney phenotypes (e.g., EYA1, SIX1, SIX5, CHD7, MASP1, TBX1), involved in BOR/BO syndrome, CHARGE syndrome, 3MC syndrome and DiGeorge syndrome." (PMID 32585897, 2020). "In the serum of a 3MC syndrome patient lacking both proteins, functional AP was observed, and in mice deficient for MASP-1, MASP-3, and FH extensive, AP activation was observed, just like in mice deficient for FH only." (PMID 30135690, 2018). "While in humans, it was reported that the sera of 3MC syndrome patients deficient for both MASP-1 and MASP-3 lacked C4 deposition activity on mannan via the LP but exhibited lowered hemolytic activity via the AP, suggesting the existence of a backup system that activates pro-FD at least in humans." (PMID 36052069, 2022). "It should be noted, however, that in the serum of a 3MC syndrome patient, where there was neither MASP-1 nor MASP-3 present due to a mutation in the MASP1 gene, no LP activity could be detected." (PMID 30135690, 2018). "It should be however mentioned, that mice with knockout in MASP1/3 or COLEC11 genes developed normally and no defects similar to 3MC syndrome were noticed." (PMID 32751929, 2020).
COVID-19 (11 papers, 2021 to 2024). A disease caused by infection with severe acute respiratory syndrome coronavirus 2. "The overactivation of coagulation in the initial phase of COVID-19, generating high levels of D-dimers, thrombocytopenia, and moderate prothrombin time prolongation, seems to be caused by the combined action of MASP-1/MASP-2 and thrombin." (PMID 33729332, 2021). "Our results suggest that the lectin pathway is activated in COVID-19 patients, with higher levels of the specific LP activation marker MASP-1/C1-INH complex, and the joint LP/CP marker C4d in more severe cases." (PMID 37051252, 2023). "Nevertheless, MASP-1/C1-INH complex levels positively correlate with C4d and TCC/C5b-9 concentrations in COVID-19 cases in general, further validating the usage of MASP-1/C1-INH complex as a direct measure of early lectin pathway activation." (PMID 37051252, 2023). "We show that the lectin pathway is activated in acute COVID-19, indicated by the correlation between complement activation product levels of the MASP-1/C1-INH complex (p=0.0011) and C4d (p<0.0001) and COVID-19 severity." (PMID 37051252, 2023). "The median MASP-1/C1-INH complex levels observed in COVID-19 cases were 38% increased (median levels in cases vs. controls: 39.7 vs. 54.5 ng/mL), and C4d levels were 67% elevated when compared to HCs (median levels in cases vs. controls: 2.26 vs. 3.78 ng/mL)." (PMID 37051252, 2023). "The newly developed assays were used to measure C1s/C1-INH complex and MASP-1/C1-INH complex levels in healthy individuals (n=96) as well as in a total of 414 COVID-19 patients." (PMID 36420270, 2022). "MASP-1 and/or MASP-2 present an increased expression in patients with COVID-19 risk factors: diabetes, arterial hypertension and cardiovascular disease, chronic kidney disease, chronic obstructive pulmonary disease, and cerebrovascular disease." (PMID 33729332, 2021). "Unlike other CS components already associated with COVID-19, routine analysis of hospitalized patients for the presence/concentration of MASP-1 has not been carried out." (PMID 33729332, 2021). "Furthermore, studies investigating MASP1 and MASP2 polymorphisms that may modulate the levels of MASPs in COVID-19 patients, can contribute to a greater understanding of the disease." (PMID 33729332, 2021). "The concentration of lectin pathway-specific products, such as the MASP-1/C1-INH complex, have been correlated with COVID-19 severity." (PMID 38368584, 2024). "MASP-1/C1-INH complex levels were measured in both cohorts and significantly higher concentrations were observed in hospitalized COVID-19 patients compared to healthy controls (Kruskal-Wallis test: p=0.0008)." (PMID 37051252, 2023). "Early, specific lectin pathway activation marker MASP-1/C1-INH complex, and C4d, a marker of common CP and LP activation, are elevated in COVID-19 when compared to healthy controls (HC)." (PMID 37051252, 2023). "Even if we did not measure those alternative PRMs in the scope of our study, our results suggest that they might still be able to increase lectin pathway activation, resulting in increased levels of MASP-1/C1-INH complex and C4d in COVID-19 patients." (PMID 37051252, 2023). "Furthermore, we found MASP1, the downstream mediator of MBL2, to be increased in plasma from COVID-19 ICU patients compared with sepsis patients." (PMID 34099652, 2021). "To date, neither MASP-1 concentrations nor MASP1 polymorphisms have been investigated in the inflammatory and/or hematological processes of COVID-19." (PMID 33729332, 2021). "Measurements showed increased C1-INH complex levels in COVID-19 patients when compared to healthy controls, with a mean concentration of 2407 ± 1283 ng/mL C1s/C1-INH complex (Mann-Whitney U test: p<0.0001) and 51.5 (33.5-76.1) ng/mL MASP-1/C1-INH complex (Mann-Whitney U test: p<0.0001)." (PMID 36420270, 2022).
COVID-19 (continued). "Notably, correlations between MASP-1 and Map19 and between MASP-3 and MAp19 were negative in COVID-19 patients but positive in dialysis controls providing further evidence that lectin protein levels are altered during COVID-19 infection." (PMID 33995410, 2021).
lupus (9 papers, 2018 to 2025). "In the present study, we generated lupus-prone MRL/lpr mice that were genetically deficient for MASP-1/3 by using a backcrossing strategy and confirmed that their sera lacked both LP and AP complement activity." (PMID 29892304, 2018). "In a research, lupus-prone MRL/lpr mice with Masp1/3 gene knockout had preserved serum C3 levels, less albuminuria, and significantly less glomerular deposition than their wild-type littermates." (PMID 37636359, 2023). "This suggests that MASP-1/3 has a significant part in the development of lupus-like glomerulonephritis in MRL/lpr mice by the lectin pathway." (PMID 37636359, 2023). "The association of LP serine proteases MASPs (MASP-1, MASP-2, and MASP-3) and MBL-associated proteins MAps (MAp19 and MAp44) with lupus characteristics has also previously been assessed." (PMID 29892304, 2018). "In the current study, we first tested if lupus-prone MRL/lpr mice also had altered activation of the LP and AP in MASP-1/3-deficient serum." (PMID 29892304, 2018). "To determine the role of MASP-1/3 in lupus nephritis, we backcrossed MASP-1/3-deficient C57BL/6 mice into lupus-prone MRL/lpr mice for eight generations, and then intercrossed the Masp1/3+/− mice." (PMID 29892304, 2018). "Our data indicate that MASP-1/3 plays essential roles in the development of lupus-like glomerulonephritis in MRL/lpr mice, most likely via activation of the LP and/or AP." (PMID 29892304, 2018). "Moreover, a recent animal study evidenced the involvement of MASP-1 in the development of lupus-like glomerulonephritis in mice." (PMID 33436777, 2021). "Although the efficiency of MASP-1-mediated cleavage in the kinin generating system is low compared to that of the plasma kallikrein-mediated cleavage, it could be important when the LP activates locally, such as in the glomeruli in lupus patients." (PMID 29892304, 2018). "In addition, several autoimmunity-related proteins are linked to coagulation (e.g., AGT, F2) and to specific ADs, such as systemic lupus erythematosus (e.g., AGT, C1S, C7, MMP2, VWF) or autoimmune rheumatic diseases (e.g., ADIPOQ, AGT, MASP1, MMP2)." (PMID 40546301, 2025). "Masp1 knockout lupus-prone MRL/lpr mice (Masp1/3−/− MRL/lpr mice) lacking both MASP-1 and its splicing isoform MASP-3 demonstrated reduced activation of LP and AP." (PMID 33574820, 2020). "Taken together, the absence of MASP-1 in addition to the absence of MASP-3 is highly beneficial to protect lupus patients from the development of glomerulonephritis." (PMID 29892304, 2018). "The direct effect of MASP-1/3 regarding complement activation on lupus may be elucidated in further studies using anti-MASP-1/3 agents, such as a specific inhibitor and anti-MASP-1/3 Ab, by suppressing MASP-1/3 therapeutically." (PMID 29892304, 2018). "We evaluated the serum level of MASPs (MASP-1 and MASP-2) in total 68 SLE patients consisting of 15 patients with biopsy-confirmed membranous lupus nephritis (M-LN), 35 patients with biopsy-confirmed proliferative lupus nephritis (P-LN), and 18 SLE patients without LN (non-LN)." (PMID 37636359, 2023). "To investigate the roles of MASP-1 and MASP-3 in lupus, we generated Masp1 gene knockout lupus-prone MRL/lpr mice (Masp1/3−/− MRL/lpr mice), lacking both MASP-1 and MASP-3, and analyzed their renal disease." (PMID 29892304, 2018). "The results presented in this report indicate that the absence of MASP-1/3 in MRL/lpr mice has a significant effect on the activation of the complement and development of lupus-like glomerulonephritis." (PMID 29892304, 2018). "Interestingly, plasma concentrations in lupus patients were higher than the healthy controls regarding MASP-1, MASP-3, and MAp44, but not MASP-2." (PMID 29892304, 2018). "Another study showed reduced levels of MASP-1 and MASP-2 in proliferative lupus nephritis and severe SLE without lupus nephritis, while in patients with membranous nephritis, the concentration of these serine proteases was the same as in healthy controls." (PMID 38338844, 2024).